INS (insulin)
Diseases named in the same sentence as INS in open-access papers (continued):
Sharing a sentence is not in itself a finding about the gene and the disease.
type 2 diabetes (continued). "On the other hand, galectin-3 levels correlated positively with insulin sensitivity and negatively with HbA1c levels in patients with type 2 diabetes." (PMID 26770660, 2016). "Real-world persistence of RAI in insulin-naïve elderly patients with type 2 diabetes was very poor when RAI was added to an OAD regimen." (PMID 27761472, 2016). "Insulin signaling regulates glucose uptake, lipid biosynthesis and cellular growth in insulin sensitive tissues, and dysfunction of this pathway drives the development of type 2 diabetes, NASH, atherosclerosis and obesity." (PMID 27618008, 2016). "Administration of OME improved and normalized dyslipidemia recorded in type 2 diabetic rats together with reduction in glucose and insulin levels." (PMID 28228803, 2016). "The rate of insulin use in type 2 diabetes increased more than six-fold in the UK between 1991 and 2010." (PMID 27152598, 2016). "Leptin is angiogenic during tumorigenesis and insulin is involved in type-2 diabetes-mediated mammary tumor progression in mice." (PMID 27028862, 2016). "In patients with type 2 diabetes (DM2) in use of insulin therapy, it optimizes blood glucose control." (PMID 27625706, 2016). "Therapeutics that promote insulin secretion have been a mainstay of type 2 diabetes treatment for many years." (PMID 26661410, 2016). "In the present study, long-term administration of BAIBA reduced fasting blood glucose and improved glucose tolerance and insulin sensitivity in mice with STZ/HFD-induced type 2 diabetes, which supports previous findings." (PMID 26907958, 2016). "In sum, in a cohort of insulin-naïve participants with Type 2 diabetes followed over a period of 17 years, an elevated level of depressive symptoms (without elevated anxiety symptoms) was associated with a 39% increased mortality risk." (PMID 27537359, 2016). "Only one small randomized controlled trial has looked at the addition of metformin to insulin in women with type 2 diabetes in pregnancy." (PMID 27435163, 2016). "The HOMA-IR is closely correlated with the insulin sensitivity index assessed by euglycemic clamp in only a few patients with type 2 diabetes." (PMID 26752053, 2016). "We found, that complete remission in type 2 diabetes was observed after sleeve gastrectomy in a follow-up of 6 months as 90.9 % and 1 year as 95.4 %; previously 37.5 % of these patients were insulin dependent and 62.5 % were using oral antidiabetic drugs." (PMID 27186461, 2016). "Dietary guidelines on macronutrient intake to improve glucose-insulin profiles and reduce or prevent type 2 diabetes generally recommend increasing foods rich in monounsaturated fat (MUFA) and reducing saturated fat (SFA)." (PMID 27434027, 2016). "Studies on the flexibility of ectopic lipids in patients are mainly limited to insulin resistant, i.e., glucose intolerant patients or patients with type 2 diabetes, but this data is mainly limited to long-term interventions." (PMID 27649157, 2016). "Protein tyrosine phosphatase 1B (PTP1B) is a novel therapeutic target for type-2 diabetes, which negatively regulates the insulin signaling transduction." (PMID 26808535, 2016). "We sought to evaluate the effect of MA correction on endogenous insulin action in diabetic type 2 (DM2) CKD patients." (PMID 27770799, 2016). "Due to the progressive beta-cell dysfunction that characterizes type 2 diabetes, many diabetic patients eventually require insulin replacement therapy despite oral anti-diabetic treatment." (PMID 27827363, 2016). "Txnip expression is elevated in skeletal muscle of individuals with impaired glucose tolerance or type 2 diabetes, and Txnip expression is inversely correlated with insulin-stimulated glucose uptake in human insulin/glucose clamp studies." (PMID 27725089, 2016). "Therapeutic agents for Asian type 2 diabetes need to not only enhance insulin sensitivity but also potentiate β-cell function and mass." (PMID 26978400, 2016).
type 2 diabetes (continued). "Type 2 diabetes affects approximately one in 12 of the adult population and usually involves changes in both insulin secretion and insulin action." (PMID 27338626, 2016). "In a previous study, PT ameliorated the insulin sensitivity and β-cell dysfunction in type 2 diabetic mice." (PMID 27869712, 2016). "We present herein a case of chylomicronemia accompanied by acute exacerbation of type 2 diabetes but dramatically recovered after insulin therapy." (PMID 27652072, 2016). "Reduction of AUC−15–240 min-insulin in type 2 diabetes and reduction of AUC−15–240 min-C-peptide in type 2 diabetes and controls reached statistical significance." (PMID 26704625, 2016). "Here, we cultured human primary myotubes from donors with a broad range in metabolic health status and insulin sensitivity, i.e. ranging from young healthy endurance trained athletes to type 2 diabetes patients." (PMID 27756900, 2016). "Significantly, PFKFB3/iPFK2 is involved in the effect of rosiglitazone, one of the only two currently prescribed medicines as insulin-sensitizers for the treatment of type 2 diabetes, on suppressing intestinal inflammation." (PMID 27387960, 2016). "In the early stages of type 2 diabetes, insulin production is normal or increased in absolute terms, but this is insufficient to control blood glucose levels due to reduced insulin sensitivity." (PMID 27379014, 2016). "In the context of type 2 diabetes, there are extensive data showing clear insulin resistance in skeletal muscle, as seen in less insulin stimulation of glucose uptake, oxidation, or activation of Akt." (PMID 26908121, 2016). "In conclusion, the FINDRISC predicts impairment in insulin secretion and insulin sensitivity, the conversion to type 2 diabetes, drug-treated hypertension, CVD events and total mortality." (PMID 27851812, 2016). "Adult onset diabetes or type 2 diabetes is best described by the presence of insulin resistance coexisting with impaired insulin secretion." (PMID 26909486, 2016). "Type 2 diabetes defined as non-insulin-dependent or adult-onset diabetes originates from the body's inability to consume insulin which is frequently accompanied with weight gain and physical inactivity." (PMID 28004008, 2016). "While children present with both low fasting blood glucose and insulin values, more than 90% of the adult patients show abnormally high fasting insulin levels resulting in type 2 diabetes in half of the patients." (PMID 27044324, 2016). "This low persistence rate is similar to that reported in a study that used the same measure to evaluate RAI persistence in an adult type 2 diabetes population when adding RAI to a basal insulin regimen (19.1%)." (PMID 27761472, 2016). "The thiazolidinedione rosiglitazone, a peroxisome proliferator activated receptor gamma (PPARγ) agonist, is an insulin sensitizing agent that improves glycaemic control and a variety of other metabolic disturbances in patients with type 2 diabetes." (PMID 26734075, 2016). "Decreases in insulin secretion and insulin sensitivity occur during the development of type 2 diabetes." (PMID 27070590, 2016). "Type 2 diabetes is a metabolic disease categorized, primarily, by reduced insulin sensitivity, β-cell dysfunction, and elevated hepatic glucose production." (PMID 27274997, 2016). "In conclusion, this new analysis of pooled clinical trial data showed that there was no increased risk of MACE associated with pramlintide therapy versus comparator treatment in patients with type 2 diabetes using insulin." (PMID 28702246, 2016). "Type 2 diabetes is a progressive metabolic disorder of multiple aetiology resulting from defects in insulin secretion from the beta cells and/or insulin resistance in peripheral tissues leading to chronic hyperglycaemia." (PMID 27669277, 2016). "The findings of the current retrospective pooled analysis add to the body of safety data on pramlintide use in patients with type 2 diabetes inadequately controlled on insulin." (PMID 28702246, 2016).
type 2 diabetes (continued). "Hypoglycemia is the principal barrier for achieving optimal, let alone normal, glycemic control for indefinite periods of time in patients with type 1 diabetes and advanced insulin-requiring type 2 diabetes." (PMID 26521082, 2016). "We identified 12,020 subjects with type 2 diabetes who progressed to insulin treatment, alone or in combination with metformin." (PMID 27152598, 2016). "In fact, in a murine model of type II diabetes mellitus, downregulation of mitochondrial HSPD1 caused hypothalamic insulin resistance and mitochondrial dysfunction consequent to disruption of leptin signaling." (PMID 27125468, 2016). "This is interesting, as insulin has been shown to improve cEPCs number and function in type 2 diabetes." (PMID 27561827, 2016). "Insulin-stimulated cardiac glucose uptake and their utilization are also impaired in type 2 diabetic hearts." (PMID 27014078, 2016). "Individuals with new onset type 2 diabetes receiving exenatide for 24 weeks improved insulin sensitivity, while following a diet and exercise regimen." (PMID 27398720, 2016). "It has been suggested that in subjects with higher concentrations of uric acid and increased insulin secretion who are observed in the early stage of type 2 diabetes, the depletion of β-cell function is more rapid." (PMID 27166795, 2016). "Using the data available within the databases, it was not possible to distinguish between women being treated for type 1 and type 2 diabetes, especially as women with type 2 diabetes are increasingly being treated with insulin." (PMID 27192491, 2016). "Seven patients (24.1%) had type 2 diabetes treated with oral antidiabetic drugs and only one patient was taking insulin." (PMID 27725831, 2016). "In this study, changes in number of NK cells in the patients with type 2 diabetes and a coexisting colon cancer were accompanied by increased levels of fasting insulin and high HOMA-IR value." (PMID 27303448, 2016). "Oral administration of DSC108 significantly suppressed the rises in blood glucose levels after glucose load in wild-type mice and improved glucose tolerance in the Goto-Kakizaki (GK) rat, a model of type 2 diabetes with impaired insulin secretion." (PMID 27764176, 2016). "Type-1 diabetes results from an autoimmune attack of insulin-producing pancreatic β-cells, while type-2 diabetes is mainly due to insulin resistance (IR)." (PMID 27164093, 2016). "TDD was correlated with blood glucose reduction in response to intravenous insulin infusion in Chinese new onset patients with type 2 diabetes." (PMID 26697503, 2016). "In line with this, a higher muscle ceramide content and lower insulin sensitivity was observed in Offsprings from type 2 diabetic patients compared to matched Controls." (PMID 27777958, 2016). "Baseline characteristics of the study population (insulin naïve people with Type 2 diabetes), stratified by HADS-Anxiety and HADS-Depression subgroups." (PMID 27537359, 2016). "Of the 174 (117 men, 57 women) patients diagnosed with type 2 diabetes, 56 were administered insulin therapy." (PMID 26955641, 2016). "Thiazolidinediones (TZDs or glitazones) are ligands of the nuclear receptor transcription factor peroxisome proliferator-activated receptor gamma (PPAR gamma) that have recently been developed as insulin sensitizers to treat patients with type 2 diabetes." (PMID 26770984, 2016). "We also found that DSC108 improves glucose tolerance in the GK rat, a model of type 2 diabetes with impaired insulin secretion." (PMID 27764176, 2016). "Type 2 diabetes mellitus (T2DM) is one of the most prevalent metabolic diseases worldwide caused by insulin resistance of the peripheral tissues and impaired insulin secretion of pancreatic β-cells." (PMID 26918025, 2016). "As a progressive disease type 2 diabetes requires intensification of treatment over time, from lifestyle modification through oral therapy in different regimens, to insulin treatment." (PMID 27724912, 2016).
type 2 diabetes (continued). "The top ranked behaviour for people with Type 1 diabetes was to ‘take insulin as required’ and for people with Type 2 diabetes was to ‘attend and engage with structured education programmes’." (PMID 29062515, 2016). "Although insulin treatment has diversified in recent years, the literature on the utilization of healthcare services among patients with type 2 diabetes undergoing different insulin therapy regimens is scarce." (PMID 26759271, 2016). "Gold standard type 1 diabetes was defined as continuous insulin treatment within 3 years of diagnosis and absolute insulin deficiency (UCPCR<0.2 nmol/mmol ≥5 years post-diagnosis); all others classed as having type 2 diabetes." (PMID 27080317, 2016). "Women who required insulin to manage GDM were more likely to develop type 2 diabetes (RR 3.66 [95% CI 2.78, 4.82]; I2 = 71%) compared with those managed without insulin." (PMID 27073002, 2016). "Increased TLR4 expression leads to type 2 diabetes by reducing insulin secretion by β-cells and together with TLR2 and TLR9 contribute to the development of neurological disorders like schizophrenia and autism." (PMID 27307950, 2016). "Type 2 diabetes (T2D) results from failure of the insulin‐producing β‐cells to compensate for increased metabolic demands, resulting in impaired glucose homeostasis and decreased β‐cell mass." (PMID 27670405, 2016). "There are more than 90% cases with type 2 diabetes where the cells in the body show reduced reaction to insulin (insulin resistance)." (PMID 27904436, 2016). "Adipocytes in the accumulated fat tissues, especially around waist area and visceral organs, release several cytokines which reduce the sensitivity of several cell types to insulin leading to insulin resistant and type 2 diabetes." (PMID 27057179, 2016). "The vast majority of patients (262, 98.1%) had type 2 diabetes, with 46 (17.2%) requiring insulin as part of their treatment." (PMID 27907053, 2016). "In type 2 diabetes, the insulin signaling cascade is impaired in the insulin-responsive tissues: skeletal muscle, adipose tissue, and liver." (PMID 27294151, 2016). "Studies from cellular, animal and human model for Type 2 diabetes have revealed clear impairment in insulin signaling cascade towards GLUT4 translocation." (PMID 28248217, 2016). "Of medical importance, the discovery of the DPP-4 protease resistant exendin-4 from venom of Heloderma suspectum paved the way for the successful development of GLP-1 analogues as important treatments for insulin resistant type 2 diabetics." (PMID 27898108, 2016). "Some studies have reported differences in the pathophysiology of type 2 diabetes between Japanese patients and Caucasian patients, with that of Japanese patients being more related to reduced insulin secreting capacity than insulin resistance." (PMID 27252787, 2016). "Obesity and type 2 diabetes are interrelated and the current understanding is that as obesity develops, the body becomes increasingly insulin resistant which can progress into type 2 diabetes." (PMID 26751381, 2016). "The PPAR activation in type 2 diabetic patients results in a marked improvement in insulin and glucose parameters, resulting from an improvement of whole-body insulin sensitivity." (PMID 26901760, 2016). "Male HFD rats exhibit all clinical characteristics of type-2 diabetes seen in other diet-induced rodent T2D models, including increases in circulating insulin." (PMID 26823968, 2016). "As such, normalisation of blood glucose levels has also been shown to restore GIP insulin secretory function in both rodents and humans with in type 2 diabetes." (PMID 27032106, 2016). "High-5HT animals also developed a type 2 diabetes (T2D) phenotype with increased: plasma insulin, glucose, hemoglobin A1c, body weight, visceral fat, β-cell pancreatic islets size, serum cholesterol, and decreased muscle strength." (PMID 26907598, 2016).
type 2 diabetes (continued). "This observational cohort study showed that GLP-1 RA treatment resulted in a sustained reduction of weight, HbA1c and TDD in obese insulin-using type 2 diabetes patients in a real life setting." (PMID 26597956, 2016). "Pulsatile insulin secretion enhances the role of the liver in glucose homeostasis, and insulin pulsatility is impaired in patients with type 2 diabetes." (PMID 27788129, 2016). "This notion is consistent with the numerical works that examined the effects of insulin infusion rate changes on patients with SH and on patients with type 2 diabetes who were receiving continuous enteral feedings and SQ insulin therapy." (PMID 26819233, 2016). "Type 2 diabetes mellitus (T2DM) is a multidimensional metabolic disease, characterized by increases in blood sugar or hyperglycemia and is caused by a disorder in insulin secretion or functioning or both." (PMID 27907074, 2016). "Despite the promising efficacy of the glitazones (TZDs) in improving insulin sensitivity and management of type 2 diabetes, the serious concern over their cardiovascular safety has urged many countries to remove all approved TZDs from the market." (PMID 26770984, 2016). "Our results have potential implications for enhancing insulin pulsatility and therefore mitigating the development of type 2 diabetes." (PMID 27788129, 2016). "The purpose of this study was to assess total daily insulin requirement and the impact factors in newly diagnosed patients with type 2 diabetes, who were on transient CSII therapy in China." (PMID 26697503, 2016). "Age at diagnosis was younger (50 years), and a greater proportion were on insulin (alone or in combination) than those classified as “probable” type 2 diabetes (71% versus 10%)." (PMID 27631769, 2016). "In newly diagnosed Chinese patients with type 2 diabetes, insulin secretion, in particular at early phase, is normally reduced due to the impaired β-cell function." (PMID 26697503, 2016). "Prior hypoxic exposure is also known to increase two-compartment models of insulin sensitivity with acute intermittent hypoxia shown to improve glucose control in patients with type 2 diabetes." (PMID 27274997, 2016). "Omega-3 polyunsaturated fatty acids (n-3 PUFA) of marine origin, eicosapentaenoic acid (EPA), and docosahexaenoic acid (DHA), have been long studied for their therapeutic potential in the context of type 2 diabetes, insulin resistance, and glucose homeostasis." (PMID 27258299, 2016). "Failure in this compensatory process results in the release of insufficient insulin to cover the organism’s needs and the development of type 2 diabetes." (PMID 26474776, 2016). "Robust effects of GPR40 agonists on increasing insulin secretion and lowering blood glucose have been shown in rodent model of type 2 diabetes recently." (PMID 27121981, 2016). "Clinical studies performed in human revealed a positive correlation between plasma 26RFa and plasma insulin in obese, type 2 diabetic patients and healthy volunteers." (PMID 27965532, 2016). "They reported that decreased endogenous insulin secretion (serum CPR and IRI, and urine CPR) was an independent risk factor for sarcopenia in patients with type 2 diabetes." (PMID 27612202, 2016). "Insulin clearance is an important component of insulin metabolism, with a decrease in clearance levels predicting increased incidence of type 2 diabetes." (PMID 27846285, 2016). "In this study, we found selective impairment of insulin signalling in the hepatic PP zone in type 2 diabetes and obesity." (PMID 27708333, 2016). "Metabolic pathways included deregulated genes from the AMP-activated protein kinase (AMPK) pathway, gluconeogenesis as well as genes from insulin signaling, type II diabetes signaling, maturity onset diabetes of the young and circadian rhythm pathways." (PMID 26963617, 2016).